AKR1C3 (aldo-keto reductase family 1 member C3)
Diseases named in the same sentence as AKR1C3 in open-access papers (continued):
Sharing a sentence is not in itself a finding about the gene and the disease.
prostate carcinoma (continued). "Because compound 2 was also previously shown to inhibit CYP17, results from the present study suggest it may be possible to design dual AKR1C3/CYP17 inhibitors for potential use in the treatment of advanced prostate cancer based on a steroid scaffold." (PMID 40905588, 2025). "Genetic variants of AKR1C3 gene were correlated with risk of lung and prostate cancer, leukemia, bladder cancer, B cell non-Hodgkin lymphoma, and breast cancer." (PMID 39596349, 2024). "This indicates that the overexpression of AKR1C3 may be a biological marker for the conversion of prostate cancer from hormone-dependent to CRPC." (PMID 36794010, 2023). "From these results, we conclude that the conversion of DHEA to 5-Adiol is a viable transformation catalyzed by AKR1C3 that could likely occur in prostate cancer cells at the same level as other pathways." (PMID 37772993, 2023). "AKR1C3 is a target for treatment of breast and prostate cancer and AKR1C3 inhibition could be an effective adjuvant therapy in the context of leukemia and other cancers." (PMID 36846371, 2023). "Moreover, berberine suppressed the intracellular androgen synthesis via inhibiting the aldo-keto reductase family 1 member C3 (AKR1C3) enzyme activity, and then inhibited prostate cancer cell growth." (PMID 35889396, 2022). "As a member of the aldo-keto reductase family 1, AKR1C3 has been shown to be increased in erastin-resistant DU-145 prostate cancer cells in a recent study, suggesting that AKR1C3 might be a suppressor of cell ferroptosis." (PMID 35741758, 2022). "Splice-disrupt variants on BRCA1, AKR1C3, and KLK3 is observed in all types of prostate cancer." (PMID 35286517, 2022). "AKR1C3 is known as an epithelial-mesenchymal transition driver in prostate cancer metastasis." (PMID 34997089, 2022). "Although the connection of AKR1C3 with ROS regulation has already been indicated in prostate cancer and ESCC, these studies mainly focused on radiation resistance, and the underlying molecular mechanism of the regulatory role of AKR1C3 with ROS is not well investigated." (PMID 34065695, 2021). "A recent study revealed that AKR1C3 was upregulated in erastin-resistant DU-145 prostate cancer cells, implying that AKR1C3 may be a suppressor of cell ferroptosis." (PMID 34568444, 2021). "Among them, AKR1C1 and AKR1C3 have been reported to be upregulated in human tumors and identified as prognostic markers for various forms of cancer, including breast, colon, bladder, and prostate cancers." (PMID 34830394, 2021). "Recently, it is shown that the oncogenic transcription factor ERG, expressed by the TMPRSS2:ERG fusion gene, could upregulate the AKR1C3 expression in prostate cancer." (PMID 32226548, 2020). "Finally, we investigated the functional significance of ERRα-mediated up-regulation of AKR1C3 in activation of AR signaling in prostate cancer cells." (PMID 32226548, 2020). "Therefore, we are confident that a combination of AKR1C3 and AR inhibitory activity, as displayed by MF-15, is a powerful combination to combat prostate cancer." (PMID 32731472, 2020). "Since the expression of CYP11A1 is rather low in prostate cancer cells and hardly detectable in clinical prostate cancer tissues, we next manly investigated the significance of ERRα-enhanced AKR1C3 expression or activity in the DHT biosynthesis in AR-positive prostate cancer cells." (PMID 32226548, 2020). "Overall, these results suggest that ERRα could play a role in activation of AR signaling in prostate cancer cells via its regulation of AKR1C3 expression." (PMID 32226548, 2020). "In addition, it is known that the androgen biosynthesis enzymes AKR1C1, AKR1C2, and AKR1C3 are upregulated in prostate cancer." (PMID 29682196, 2018).
prostate carcinoma (continued). "Osteocalcin activation of GPRC6A may indirectly promote androgen synthesis through stimulation of IL-6, a cytokine that can promote androgen synthesis in prostate cancer cells through enhancing AKR1C3 transcription." (PMID 28659174, 2017). "In addition, a synergistic anti-tumor effect when indomethacin (an AKR1C3 inhibitor) is combined with either abiraterone or enzalutamide has been reported in otherwise resistant prostate cancer cell lines." (PMID 26566796, 2015). "Although the correlation index is low in this study, the data still indicate that the expression of AKR1C3 may serve as a promising biomarker for evaluating prostate cancer progression." (PMID 24571686, 2014). "The PROTAC functionalized compound is far more effective than small molecule inhibitors to induce AKR1C3 degradation and does so from 4 h post exposure and this translates to greater effects on cell viability of a variety of AKR1C3 differentially expressing prostate cancer cell lines." (PMID 38684887, 2024). "In addition, AKR1C3 binds and stabilizes the ubiquitin ligase Siah-2, inhibiting its degradation, thereby enhancing Siah-2-dependent down-regulation of the AR corepressor NCoR in prostate cancer cells." (PMID 35582223, 2020). "In prostate cancer, the overexpression of aldo-keto reductase 1C3 (AKR1C3), an enzyme involved in PG metabolism, resulted in the accumulation of PGF2α, which not only promotes prostate cancer cell proliferation but also enhances prostate cancer cell resistance to radiation." (PMID 30133566, 2018). "For BPH and PIN specimens, positive expression of AKR1C3 was observed in the stromal cells other than the epithelial cells, and for malignant prostate cancer specimens with GS greater than 6, a gradually stronger positive staining of AKR1C3 was detected in prostate cancer epithelial cytoplasm." (PMID 24571686, 2014). "To determine the magnitude of degradation of target proteins resulting from exposure to our small molecule inhibitor scaffold, we investigated the ability of inhibitor 3 and warhead 4 to degrade AKR1C3, AKR1C1/2, and ARv7 in 22Rv1 prostate cancer cells." (PMID 38684887, 2024). "AKR1C3 is upregulated in CRPC and overexpressed in cell culture in response to androgen deprivation and in prostate cancer cells made resistant to Abi and Enz." (PMID 37772993, 2023). "In our study, we found that overexpression of AKR1C3 in PCa could result in radioresistance through elimination of ROS and accumulation of PGF2α, which could not only promote prostate cancer cells' proliferation but also enhance prostate cancer cells' resiatance to radition." (PMID 27385003, 2016). "Also overexpression of AKR1C3 could result in the accumulation of prostaglandin F2α (PGF2α), which can not only promote prostate cancer cell 's proliferation but also could enhance prostate cancer cells resistance to radiation and activated the MAPK pathway and inhibited the expression of PPARγ." (PMID 27385003, 2016). "For instance, inhibiting AKR1C3, an enzyme involved in converting DHEA-S into the potent AR ligands testosterone and dihydrotestosterone (DHT), has been shown to inhibit prostate cancer cell growth in cell culture and xenograft models." (PMID 26566796, 2015). "Warhead compound 4, a small molecule inhibitor of AKR1C3, at concentration from 0.001 to 10 μM affords no reduction of cell viability in 22Rv1 prostate cancer cells after 72 h of treatment, despite its AKR1C3 IC50 = 62 nM." (PMID 38684887, 2024). "Furthermore, AKR1C3 which functions as a prostaglandin F (PGF) synthase as well as its isoforms PGF2α and 11β-PGF2α are reported to induce prostate cancer development by preventing the activation of peroxisome proliferator-activated receptor gamma (PPARγ)." (PMID 39055885, 2024). "Overall, the previous studies suggest that genistein inhibits the development and progression of prostate cancer; however, whether it inhibits the growth of CRPC through regulating AKR1C3 remains unclear." (PMID 36794010, 2023).
prostate carcinoma (continued). "We next sought to determine whether the up-regulation of the two androgen biosynthetic enzyme genes AKR1C3 and CYP11A1 could be the result of direct targeting of ERRα in prostate cancer cells." (PMID 32226548, 2020). "Therefore, inhibition of AKR1C3 and GABAA-R in prostate cancer would hypothetically potentiate conventional therapy." (PMID 32555170, 2020). "Studies suggest that AKR1C3 has a pivotal role in the radioresistance of esophageal cancer and non-small-cell lung cancer, yet the role of AKR1C3 in prostate cancer cells radiation resistance has not yet been clarified." (PMID 27385003, 2016). "Because one AKR1C3 inhibitor identified here was also previously reported to inhibit CYP17, it may be possible for future researchers to design dual AKR1C3/CYP17 inhibitors based on a steroid scaffold for potential treatment of advanced prostate cancers." (PMID 40905588, 2025). "The AKR1C3 gene, also known as type 5, 17β-hydroxysteroid dehydrogenase (17β-HSD), is a key enzyme in the last two steps of testosterone and DHT synthesis in tumor cells, with DHT deemed to promote the growth, proliferation, and metastasis of prostate cancer cells." (PMID 36794010, 2023). "We analyzed the relationship between AKR1C3 expression and the survival rate of prostate cancer patients based on the GEPIA online database to perform disease-free survival, and found that AKR1C3 may be an important factor leading to poor prognosis in prostate cancer." (PMID 36591491, 2022). "Overall, these results suggest that ERRα could function to promote the intratumoral DHT biosynthesis in prostate cancer or CRPC via its direct regulation of AKR1C3 expression and also pharmacological suppression of ERRα activity could reduce the DHT production in prostate cancer cells." (PMID 32226548, 2020). "AKR1C3 has closed relationship with many tumours,such as breast cancer, colon cancer and choriocarcinoma, yet the role of AKR1C3 in prostate cancer cells radiation resistance has not yet been clarified." (PMID 27385003, 2016). "AKR1C3, comes from the same family as AKR1C1, has not been proved to have similar functions as AKR1C1 in bladder cancer, but it is often overexpressed in prostate cancer tissues and cell lines." (PMID 38978149, 2024).
breast carcinoma (30 papers, 2012 to 2026). "Further research on AKR1C3 variants and their impact on estrogen synthesis and prostaglandin pathways is essential for understanding their role in breast cancer pathology." (PMID 40489436, 2025). "Our findings highlight AKR1C3 as a potential therapeutic target in breast cancer, particularly for individuals with H5Q mutation." (PMID 40489436, 2025). "The expression of AKR1C3, as a radioresistance-associated gene, is associated with various diseases, such as breast cancer, PC, esophageal cancer, and non-small cell lung cancer (NSCLC)." (PMID 35359392, 2022). "The enzyme AKR1C3 has many functions, which include production of prostaglandins, androgens and estrogens, and metabolism of different chemotherapeutics; AKR1C3 is thus implicated in the pathophysiology of different types of cancer, including breast cancer." (PMID 34199169, 2021). "AKR1C3 is known to be abundantly expressed in breast cancer tissues, and high levels are often associated with adverse clinical outcome." (PMID 28352233, 2017). "Aldo–keto reductase 1C3 (AKR1C3) is also linked to doxorubicin resistance in human breast cancer which resulted from activation of anti-apoptosis PTEN/Akt pathway via PTEN loss." (PMID 28352233, 2017). "Because AKR1C3 overexpression is associated with drug resistance in prostate and breast cancers, we hypothesized that suppression of AKR1C3 activity would increase the sensitivity of HCC cells to sorafenib." (PMID 38188684, 2023). "AKR1C3-mediated DOX resistance might result from the activation of anti-apoptosis PTEN/Akt pathway via PTEN loss in breast cancer." (PMID 35359392, 2022). "Previous functional analyses also showed that rs12529 (H5Q) decreases the kcat/Km for 17-ketosteroid reduction by AKR1C3, supporting its potential impact on breast cancer." (PMID 40489436, 2025). "Immunohistochemical data from the HPA database supported these findings, showing elevated PIK3R1, ESR1, and AKR1C3 levels in breast cancer tissues, aligning with their proposed roles in cancer cell proliferation and hormone regulation." (PMID 39204124, 2024). "CBM effectively prevented the inhibition of COX-1, COX-2, AKR1C1, and AKR1C2 while retaining AKR1C3 inhibition, making it a valuable molecular probe for studying AKR1C3’s role in breast cancer signaling and proliferation." (PMID 38523637, 2024). "Combining inhibitors of AKR1C3, glutathione synthesis, and/or proteasomal proteolysis has proven effective in enhancing cisplatin sensitivity in breast cancer cells." (PMID 38523637, 2024). "The increased PPARγ-dependent and decreased NFκB-dependent and ERα-dependent gene transcription resulting from AKR1C3 inhibition is predicted to inhibit breast cancer cell proliferation, making it a potential target for breast cancer treatment." (PMID 38523637, 2024). "In conclusion, understanding the mechanisms involving AKR1C3 in endocrine therapy resistance, particularly in prostate and breast cancers, is critical for developing targeted therapies that can overcome drug resistance and improve treatment outcomes." (PMID 38523637, 2024). "Given its potential contribution to breast cancer cell proliferation, AKR1C3 represents a promising therapeutic target." (PMID 38523637, 2024). "AKR1C3 and CXCL2 are ferroptosis-related genes associated with the immune microenvironment and prognosis in breast cancer." (PMID 36275721, 2022). "The results showed the AKR1C1, AKR1C2 and AKR1C3 were highly expressed in TAM-resistant breast cancer cells." (PMID 34886806, 2021). "Compared with TAM-sensitive counterparts, the expression levels of AKR1C1, AKR1C2, and AKR1C3 were up-regulated in TAM-resistant breast cancer cells." (PMID 34886806, 2021). "The function of AKR1C1, AKR1C2 and AKR1C3 genes in TAM-resistant breast cancer cells was revealed by bioinformatics analysis and further confirmed by biological experiments." (PMID 34886806, 2021).
breast carcinoma (continued). "AKR1C3 overexpression was shown in explants taken from patients with breast cancer and in the breast cancer cell line MCF-7 with developed resistance to DOX." (PMID 28283780, 2017). "Elevated expression of AKR1C3 has been identified in prostate and breast cancer and is correlated with the aggressiveness of the disease." (PMID 24934327, 2015). "The role of AKR1C3 or its products in hormone-dependent and prostaglandin-dependent cancers has been investigated in a number of systems including breast cancer, prostate cancer, endometrial cancer, and acute myelogenous leukemia." (PMID 22937138, 2012). "AKR1C3 is over-expressed in a variety of cancers, most notably prostate and breast cancer, with a correlation between expression levels and the aggressiveness of the disease." (PMID 22937138, 2012). "Combining AKR1C3 inhibitors with ATP-binding cassette transporter (ABCB1) inhibitors may overcome PTX resistance in breast cancer." (PMID 38523637, 2024). "Hence, AKR1C3 emerges as a source of proliferative signals and a potential therapeutic target for both hormone-dependent and hormone-independent breast cancer." (PMID 38523637, 2024). "Consequently, developing highly potent and specific AKR1C3 inhibitors to restore the chemosensitivity of drug-resistant breast cancer has become an essential research topic." (PMID 38675620, 2024). "KDM5B, ARSB, AKR1C3, HSD3B1, ESRRB are involved in steroid hormone metabolism and have been found to be associated with other hormone-dependent tumors, such as prostate and breast cancers." (PMID 36742386, 2023). "Furthermore, AKR1C3 mediates doxorubicin resistance in breast cancer cells by decreasing PTEN expression and subsequently activating AKT." (PMID 38188684, 2023). "In breast cancer, AKR1C3 mediates doxorubicin resistance by activating AKT via PTEN loss." (PMID 38188684, 2023). "The results suggest that the risk of death, disease progression or recurrence of breast cancer is modified by genetic variants of nuclear receptors (NR1/2, PGR), genes engaged in main metabolic pathway of doxorubicin (SLC22A16) and doxorubicin-progesterone-related gene (AKR1C3)." (PMID 32235849, 2020). "GEPIA2 database analysis revealed significant downregulation of PIK3R1, AKR1C3, and EGFR mRNAs in breast cancer tissue, with ESR1 upregulation, pointing to a complex interplay in tumorigenesis and treatment response." (PMID 39204124, 2024). "In the context of breast cancer, which involves the use of anti-estrogen agents and aromatase inhibitors in hormone receptor-positive cases, AKR1C1, AKR1C2, and AKR1C3 have been found to be upregulated in tamoxifen-resistant breast cancer cells." (PMID 38523637, 2024). "The protein expression levels of AKR1C1, AKR1C2 and AKR1C3 in TAM-sensitive and resistant breast cancer cells were compared." (PMID 34886806, 2021). "We found that compared with TAM-sensitive breast cancer cells, the expression levels of AKR1C1, AKR1C2 and AKR1C3 genes were significantly increased in TAM-resistant breast cancer cells." (PMID 34886806, 2021). "We analyzed the online microarray database Oncomine to determine the AKR1C3 mRNA expression levels in CRPC and breast cancer patients relative to normal tissue or primary disease." (PMID 24995161, 2014). "Notably, PIK3R1, AKR1C3, and EGFR mRNAs were significantly downregulated in breast cancer tissue, while ESR1 was significantly upregulated." (PMID 39204124, 2024). "The immunohistochemical findings presented in the Human Protein Atlas (HPA) database indicated elevated levels of PIK3R1, ESR1, and AKR1C3 in breast cancer tissues as opposed to normal tissues." (PMID 39204124, 2024). "AKR1C3 is a novel therapeutic target in castration-resistant prostate cancer (CRPC) and estrogen receptor (ER)-positive breast cancer because of its ability to produce testosterone and 17β-estradiol intratumorally, thus promoting nuclear receptor signaling and tumor progression." (PMID 24995161, 2014).
breast carcinoma (continued). "Five hundred nanometer TAM was used to treat breast cancer TMA-resistant cells that knocked out AKR1C1, AKR1C2 and AKR1C3 lines, its proliferation activity was significantly lower than the wild type, which directly indicated that high AKR1C1, AKR1C2 or AKR1C3 gene expression promoted TAM resistance." (PMID 34886806, 2021). "Additionally, AKR1C3, which preferentially catalyzes the reduction of A-dione, might contribute to E2 formation, as shown after its overexpression in the MCF7 breast cancer cell line." (PMID 28690541, 2017).